VDR (vitamin D receptor)
Diseases named in the same sentence as VDR in open-access papers (continued):
Sharing a sentence is not in itself a finding about the gene and the disease.
breast cancer (continued). "The mechanisms by which the calcitriol/VDR axis promotes protective actions from breast cancer are numerous, though interference with estrogen receptor signaling and with aromatase enzyme (CYP19A1) activity has been frequently described." (PMID 34003583, 2022). "Our previous study showed a stronger statistical association in the molecular subtype group of Luminal B-like tumors, compared to other subtypes, and others have found VDR expression to be predictive for women with multifocal breast cancers." (PMID 36014861, 2022). "It has been reported that miR-1204 is able to target VDR in breast cancer, leading to a poor prognosis." (PMID 36304947, 2022). "This fated transformation of a HR precursor cell to a HR+/- tumor subtype is not due to the mutations or amplifications in the genes coding for HR proteins (ER, AR or VDR), which are relatively rare events in breast cancer." (PMID 34771496, 2021). "VDR expression correlates positively with positive outcomes in luminal A breast cancer, especially in cases treated with tamoxifen—probably due to higher ER levels that correlate with more benefit form tamoxifen use." (PMID 34638264, 2021). "Because breast cancer is heterogeneous, the relevant VDR targets and potential sensitivity to vitamin D repletion or supplementation will likely differ between patient populations." (PMID 34950835, 2021). "An apparent explanation as to why higher VDR levels predict better prognosis in patients treated with TAM is that VitD sensitizes breast cancer cells to antiestrogen therapy, as also found in the present study." (PMID 34069442, 2021). "In the absence of ligand, the basal mRNA expression of CYP24A1 correlated inversely with VDR protein levels in several breast cancer cell lines and the unliganded VDR exerts a repressive action on CYP24A1." (PMID 33809117, 2021). "Similar results were reported for breast cancer cells where VDR expression was inversely correlated to cancer malignancy, also seen in colon cancer." (PMID 34206371, 2021). "Further, mammary tumors of mice fed a VitD-supplemented diet exhibited higher levels of VDR and suppression of IRE1α-JNK signaling, and markers indicative of pro-survival autophagy." (PMID 34069442, 2021). "It was also observed that, DNA methyltransferase (DNMT) inhibitor stimulated VDR expression and strengthened the anti-proliferative effect of 1,25(OH)2D3 in breast cancer cells." (PMID 34208589, 2021). "Categorization of VDR expression (either mRNA or protein) in breast cancer in relation to clinical parameters remains complicated because of the heterogeneity of breast cancer with its high frequency of genomic instability." (PMID 34950835, 2021). "Another study confirmed that the expression of the vitamin D receptor in breast cancer patients was inversely proportional to tumor aggressiveness, including tumor size." (PMID 34206371, 2021). "Another important issue is that certain breast cancer subtypes express VDR and long term clinical data will be needed to ensure that vitamin D supplementation does not have a negative therapeutic impact." (PMID 34385978, 2021). "Elevated expression of CYP24A1, an immediate target gene of VDR, has been observed in breast cancer cells with aberrant amplification of the chromosomal loci encoding the gene." (PMID 33809117, 2021). "There are also studies on human ovarian cancer cells and breast cancer cells indicating increased VDR protein abundance in response to dihydrotestosterone in vitro." (PMID 33095902, 2021). "Similar to the case of breast cancer which has a higher predisposition to growth and the development of metastases, our study shows that WM164 VDR KO cells proliferate and migrate faster than the control scramble cells type." (PMID 34206371, 2021).
breast cancer (continued). "The availability of genetic data in projects such as ENCODE and large tumor data sets including The Cancer Genome Atlas (TCGA) has facilitated annotation of the VDR gene in human breast cancers in the context of clinical outcomes including survival." (PMID 34950835, 2021). "Breast cancer patients (n = 581) in four different datasets were divided into those expressing higher (above median) and lower levels of VDR in pretreatment ER+ tumors." (PMID 34069442, 2021). "We show here that ER+ breast cancer patients with a higher than average level of VDR expression in their pretreatment tumor survived significantly longer than patients with lower tumor VDR expression." (PMID 34069442, 2021). "In a preclinical mouse model, dietary VitD supplementation induced VDR activation and reduced carcinogen-induced ER+ mammary tumor incidence." (PMID 34069442, 2021). "We identified DEGs in ER+ breast cancer patients from four publically available datasets whose tumors contained higher and lower than median levels of VDR." (PMID 34069442, 2021). "VDR action considerably affects the function of breast tissue and plays an important role in breast cancer." (PMID 34638264, 2021). "For instance, DNM3OS downregulates Vitamin D receptor (VDR), and VDR is capable of upregulating Suppressor of fused gene (SuFu), while SuFu is an inhibitor of progression of breast cancer." (PMID 33745450, 2021). "In vitro, treatment of breast cancer cell lines with demethylating agents coordinately enhanced the expression of VDR and sensitivity to 1,25D‐mediated growth inhibition." (PMID 34950835, 2021). "Here, we found that higher VDR expression in ER+ breast cancers predicted significantly longer recurrence-free survival in patients treated with TAM." (PMID 34069442, 2021). "Vitamin D displays anticarcinogenic properties, and the expression of its receptor (VDR) has been found in different molecular subtypes, being about 30–40 % of TN breast cancer (TNBC) positive to it." (PMID 34034728, 2021). "Contradictory studies also suggested fluctuations in the expression levels of VDR and miR-125b, evidenced by the reduced expression of miR-125b and high expression levels of VDR in advanced breast cancers." (PMID 34771496, 2021). "This was the first such evidence of VDR in any cancer cell and generated particular interest because of the propensity of breast cancer to metastasize to bone and induce hypercalcemia." (PMID 34950835, 2021). "From multivariate survival analysis, high VDR tumor expression was proved to be the most and the first independent prognostic factor on overall survival of breast carcinoma patients i.e VDR is a favorable prognostic indicator for breast carcinoma." (PMID 33906311, 2021). "High VDR tumor expression is the most independent prognostic factor on overall survival of breast carcinoma patients." (PMID 33906311, 2021). "They detected hypermethylated CpG islands upstream and near the transcription start site of the VDR gene and their demethylation resulted in an increase in VDR mRNA levels in breast cancer cell lines." (PMID 32456160, 2020). "There are convincing data of the VDR gene in different studies, but to obtain sufficient information regarding the use of vitamin D supplements to prevent or treat breast cancer, is needed more research." (PMID 32986367, 2020). "Remarkably, in breast cancer and papillary thyroid carcinomas, VDR expression is found to be very high." (PMID 32679655, 2020). "Genomic profiling of murine mammary tumor cells with differential VDR expression identified 35 transcripts that were altered by the 1,25D3-VDR complex including Hyaluronan Synthase-2 (Has2)." (PMID 32774770, 2020). "Elevated levels of NCOR2 have been detected in breast cancer and prostate cancer, promoting cancer progression by suppressing vitamin D3 receptor (VDR) responsiveness 59-61." (PMID 32550907, 2020).
breast cancer (continued). "Last, in MCF-7 breast cancer cells, miR-125b downregulates VDR expression, by conferring a pharmacological resistance to vitamin D." (PMID 32560347, 2020). "These authors concluded that VDR cannot be considered as a strong prognostic factor in breast cancer." (PMID 32456160, 2020). "The treatment of breast cancer cells with 5-aza-2′-deoxycytidine (5-aza-dC), a DNA demethylation agent, restored the full length VDR transcript in breast cancer cells." (PMID 32456160, 2020). "In summary, the effects of vitamin D in breast cancer depend on its receptor, but VDR signaling is highly heterogeneous and incompletely known both in normal mammary glands and breast tumors." (PMID 32456160, 2020). "These authors demonstrated that the overexpression of miR-125b decreased the level of VDR in breast cancer MCF-7 cells." (PMID 32456160, 2020). "The method reveals that ESR1, FGFR2, VDR, CNTNAP2, and BRCA2 have a weak association with sporadic breast cancer in the Uruguayan population." (PMID 33126731, 2020). "It is accepted that VDR in breast cancer cells is necessary and sufficient for the tumor-suppressive effects of vitamin D." (PMID 32456160, 2020). "Then, it was suggested that the transcriptional repression and protein down-regulation of KCa1.1 channels partly contributes to the anti-proliferative effect of the VDR agonist on breast cancer cells." (PMID 32210800, 2020). "On the other hand, it has been shown that human VDR CpG island becomes methylated in breast cancer and treatment with demethylating agents restored the VDR expression and susceptibility to differentiation therapy using 1,25D." (PMID 32872475, 2020). "It was shown that the overexpression of miR-214 decreased VDR-mediated signaling in breast cancer cell lines." (PMID 32456160, 2020). "Several studies have reported that VDR agonists inhibit the formation of floating spheroids called mammospheres (a feature attributed to CSCs) in breast cancer stem-like cells obtained from established cell lines." (PMID 32854355, 2020). "Certain studies showed that in breast cancer, the vitamin D receptor (VDR) acts as a master transcriptional regulator of many genes involved in autophagy." (PMID 31141879, 2019). "The ApaI VDR polymorphisms was associated with plasma LDL-C levels and muscle mass changes in breast cancer survivors supplemented with vitamin D3." (PMID 31395070, 2019). "Women with VDR-positive breast tumors have a better breast cancer-specific survival compared to women with VDR-negative tumors." (PMID 31358030, 2019). "MiR-1204 has been shown to promote tumorigenesis, EMT, and metastasis in breast cancer by targeting the vitamin D receptor gene (VDR)." (PMID 31508377, 2019). "The estrogen receptor in unifocal breast cancer and the vitamin D receptor in multifocal breast cancer were especially identified as an independent prognostic marker for overall survival, when adjusted for age, grading, and staging." (PMID 31731733, 2019). "Only a few studies have reported on breast cancer VDR expression in relation to tumor prognostic factors and breast cancer survival." (PMID 31358030, 2019). "The effects of different concentrations of cytokines and VDR agonists on breast cancer cell proliferation were evaluated using the XTT method." (PMID 31093512, 2019). "VDR expression was studied in relation to established tumor-related prognostic factors and breast cancer-specific mortality." (PMID 31358030, 2019). "Even though expression of VDR in mammary gland and breast tumors has been identified in the early 80s, the evidence for correlation between breast cancer sensitivity to vitamin D3 and the expression of VDR is still controversial." (PMID 31141879, 2019). "In correlation, PTPH1 mediated stimulation of breast cancer cell growth was dependent on its stimulatory effect on the VDR protein." (PMID 30875834, 2019).
breast cancer (continued). "Future studies ought to investigate the combined effect of VDR expression and serum levels of vitamin D in relation to breast cancer prognosis." (PMID 31358030, 2019). "It was shown that Snail1 and Snail2 can bind to E-boxes in the proximal promoter region of the VDR gene to recruit co-repressors that inhibit the transcription of VDR in colon and breast cancer cells." (PMID 29657326, 2018). "The present study explored the effect of vitamin D on breast cancer cells, including their viability, apoptosis, and VDR expression." (PMID 30314996, 2018). "Expression level of vitamin D receptor (VDR) negatively correlates with metastasis in breast cancer, and suppression of VDR by TNFα can mediate the prometastatic effects of TAMs through enhancement of the β-catenin pathway." (PMID 29651445, 2018). "Calcitriol, as well as other VDR agonists, are well-known inducers of apoptosis and cell cycle arrest and are inhibitors of metastatic invasion of breast cancer cells, as determined by in vitro methods." (PMID 30037009, 2018). "By using a stable VDR knockdown approach in vitro and in vivo in mouse models, our study demonstrates that the cytoplasmic VDR plays an important role in breast cancer cell growth." (PMID 28460457, 2017). "The MCF-7 breast cancer cell line expresses an abundance of endogenous VDR, which makes it difficult to achieve efficient VDR knockdown." (PMID 28460457, 2017). "Knockdown of the VDR in MCF-7 breast cancer cells reduced growth in ligand-free conditions, suggesting that the VDR functions independently of 1,25D3 binding to promote cell growth in vitro." (PMID 28460457, 2017). "To explore the potential for clinical translation, we administered a vitamin D analogue, VDR agonist paricalcitol, to cultured breast cancer cells and a mouse model of breast cancer." (PMID 28423536, 2017). "Applying this method to six different groups of breast cancer patients, we identified a core set of pathways, including glutathione conjugation, vitamin D receptor, purine metabolism, mitotic prometaphase, and steroid hormone biosynthesis." (PMID 28957314, 2017). "This study analyzed VDR, RXR and PPARγ by immunohistochemistry in BRCA1 associated (n = 38) and sporadic breast cancer (n = 79)." (PMID 28427429, 2017). "In conclusion, this is the first study to describe VDR, RXR and PPARγ in BRCA1 mutated breast cancer." (PMID 28427429, 2017). "This new mechanism of VDR action in breast cancer cells contrasts the known anti-proliferative nuclear actions of the VDR-vitamin D ligand complex." (PMID 28460457, 2017). "We therefore knocked down VDR expression in the human breast cancer cell line MCF-7 and followed up with clonal selection to generate highly efficient knockdown clones." (PMID 28460457, 2017). "To further elucidate the function of the VDR in MDA-MB-231 breast cancer cells and the underlying molecular events, we next assayed global gene expression profiles comparing MDA-VDR-KD with MDA-NT cells in vitro." (PMID 28944088, 2017). "Vitamin D inhibits breast cancer growth through activation of the vitamin D receptor (VDR) and via classical nuclear signaling pathways." (PMID 28460457, 2017). "In this regard, the stress-activated protein kinases p38 and JNK can stimulate VDR promoter activity in human breast cancer cells, independently of 1,25D334." (PMID 29097745, 2017). "Alimirah and co-workers reported that a vitamin D receptor suppressed miR-214 but that the overexpression of miR-214 activated the hedgehog pathway to promote breast cancer progression." (PMID 29093516, 2017). "SNPs of VDR gene have been shown correlated with cancers of the breast, prostate, colon, ovarian, melanoma and other malignancies." (PMID 28489590, 2017). "Calcitriol and/or its analogs induce the up-regulation of VDR and AR as well as the down-regulation of ERα in prostate and/or breast cancer cells." (PMID 27973439, 2016).
breast cancer (continued). "The aim of the present study is to provide new mechanistic insights into the action of VDR agonists in the repression of KCa1.1 transcription and promotion of KCa1.1 protein degradation in breast cancer cells." (PMID 27973439, 2016). "The down-regulation of KCa1.1 is responsible, at least in part, for the antiproliferative effects induced by the VDR stimulation in KCa1.1-positive human breast cancer cells." (PMID 27973439, 2016). "The objective was to perform a meta-analysis to summarize the available evidence from prospective nested case-control studies on the association of vitamin D receptor (VDR) polymorphism and the risk of breast cancer." (PMID 27149457, 2016). "Low serum levels of calcitriol are associated with the progression and a high incidence of triple negative breast cancer (TNBC), and VDR-positive breast cancer patients have significantly longer disease-free survival." (PMID 27973439, 2016). "There seems to be also an association between vitamin D receptor (VDR) gene polymorphisms and the breast cancer risk." (PMID 26985904, 2016). "Of note, 1,25(OH)2D3 treatment protects against TNF-α-induced VDR loss, suppresses TGF-β1-promoted increase in the migration capacity of cultured breast cancer cells, and inhibits lung metastasis in an orthotopic breast cancer mouse model." (PMID 26880977, 2016). "In breast cancer cells, VDR agonists regulate the pre-mRNA splicing of the VD target gene and miRNA production." (PMID 27973439, 2016). "VDR agonists such as calcitriol and its analogs have been shown to exert the potent antiproliferative effects in breast cancer cells." (PMID 27973439, 2016). "It has been shown that SNAIL1 and SNAIL2 downregulate VDR gene expression and abrogate the antitumoral action of 1,25(OH)2D3 in human osteosarcoma and breast cancer cells." (PMID 26880977, 2016). "We examined the expression levels of VDR transcripts in seven human breast cancer cell lines, MDA-MB-453, YMB-1, MCF-7, BT549, Hs578T, MDA-MB-231, and MDA-MB-468, using a quantitative real-time PCR assay." (PMID 27973439, 2016). "VDR signaling has been shown to inhibit the metastatic potential of human and mouse breast cancer cells." (PMID 26008979, 2015). "Enhanced expression of MMP7 in MMTV-Ron VDR−/− mammary tumors and, conversely, reduced expression in R7 cells treated with 1,25D3 suggests a mechanism by which ligand-dependent VDR signaling delays tumor formation and mitigates progression." (PMID 26008979, 2015). "Herein we demonstrate that VDR limits Ron-induced mammary tumor initiation and growth by decreasing active β-catenin levels and through a reduction in β-catenin target genes." (PMID 26008979, 2015). "VDR ablation accelerated mammary tumor onset and led to tumors that exhibited a desmoplastic phenotype and enhanced metastases." (PMID 26008979, 2015). "This was further verified by Western analysis in the MMTV-Ron VDR−/− mammary tumors showing enhanced active β-catenin (ABC) expression, correlating with higher protein levels of c-Myc and Cyclin D1." (PMID 26008979, 2015). "TCF-4 is transcriptionally regulated by VDR in murine colon and breast cancer cells for growth inhibition." (PMID 26008979, 2015). "In agreement with other reported papers, SKBR3, MDA-MB-468 and BT549, characterized by AA Cdx2 status, showed a higher level of VDR in comparison to the other 5 ER(–) breast cancer cell lines." (PMID 25849303, 2015). "Analogous to previous studies in colon cancer showing direct interaction of VDR and β-catenin, we found that active β-catenin had significantly less interaction with the cyclin D1 promoter after 1,25D3 treatment in mammary tumor cells." (PMID 26008979, 2015). "To understand the role of VDR in the regulation of Ron-induced tumorigenesis, we utilized R7 mammary tumor cells and the human breast cancer cell line, T47D, with and without a targeted Ron knockdown (KD)." (PMID 26008979, 2015).